ACTR3BP5 (ACTR3B pseudogene 5)
Gene: Processed pseudogene on chromosome 10 (38,696,424 to 38,697,902, forward strand). Ensembl gene ENSG00000227264.
Diseases named in the same sentence as ACTR3BP5 in open-access papers:
ACTR3BP5 is named in the same sentence as 2 diseases in open-access papers, as found by Europe PMC text mining. Sharing a sentence is not in itself a finding about the gene and the disease. The quoted sentences say what the papers report.
cancer (1 paper, 2021). A tumor composed of atypical neoplastic, often pleomorphic cells that invade other tissues. "HHIPL2, XPO1, SALRNA1, ZBTB45, ANP32AP1, ACTR3BP5, LOC100129138, GPR45, and CAB39L gene deletions were associated with non-cancer subjects without FCH (p < 0.05), while RAB9BP1, LOC101928523, and MALRD1 gene deletions were related to non-cancer patients with FCH (p < 0.05)." (PMID 33431054, 2021).
ACTR3BP5 also shares sentences with these, for which no sentence is quoted: genetic diseases (1 paper).